CD47 (CD47 molecule)
Diseases named in the same sentence as CD47 in open-access papers (continued):
Sharing a sentence is not in itself a finding about the gene and the disease.
acute myeloid leukemia (continued). "In these treatment regimens, CD47-targeted agents, playing either major or supportive roles, demonstrated superiority to conventional therapies, particularly in the treatment of acute myeloid leukemia (AML)." (PMID 41383500, 2025). "The humanized CD47 antibody Hu5F9-G4 (Magrolimab) has demonstrated enhanced phagocytosis of tumor cells in vitro and therapeutic effectiveness in vivo, particularly in acute myeloid leukemia (AML) and myelodysplastic syndromes (MDS)." (PMID 40070841, 2025). "Further exploration of the GEPIA database revealed that CD47, CTSZ, and SLC11A1 were highly expressed in various cancers, such as glioma, acute myeloid leukemia-like tumors, and pancreatic cancer." (PMID 40129966, 2025). "CD38 and CD47 are also expressed in other hematologic cancers, such as T-cell acute lymphoblastic leukemia (T-ALL) and acute myeloid leukemia (AML)." (PMID 38983860, 2024). "In preclinical models of acute myeloid leukemia (AML) and myelodysplastic syndrome (MDS), CD47 blockade has demonstrated improvements in antitumor responses." (PMID 38299154, 2023). "Cluster of Differentiation 47 (CD47) is believed to actas an anti-phagocytic marker that is highly expressed on multipletypes of human cancer cells including acute myeloid leukemia (AML)and lung and liver carcinomas, allowing them to escape phagocytosisby macrophages." (PMID 36632842, 2023). "However, in 2019, a clinical trial about the combination treatment of the CD47 antibody and azacytidine for acute myeloid leukemia (AML) and myelodysplastic syndrome (MDS) indicated high treatment efficacy and high ADRs." (PMID 37138855, 2023). "Clinical studies confirm the importance of inhibiting the CD47/SIRPα interaction in various hematological malignancies, including myelodysplastic syndrome (MDS), acute myeloid leukemia (AML), and relapsed/refractory non-Hodgkin’s lymphoma (R/R-NHL)." (PMID 35978372, 2022). "In acute myeloid leukemia (AML), it was reported that the self-renewing leukemia stem cells more highly expressed CD47 than bone marrow hematopoietic stem cells (HSCs) and multipotent progenitor (MPP) cells." (PMID 34584838, 2021). "Indeed, though CD47 blockade therapies have achieved early therapeutic efficacy in acute myeloid leukemia (AML) and myelodysplastic syndrome (MDS) patients in clinical trials, this strategy has so far struggled in coping with solid tumors." (PMID 33790906, 2021). "CD47 antibodies, such as the humanized B6H12 (often referred as B6H12.2) and BRIC126 have been shown to be effective in pre-clinical mouse models of acute myeloid leukemia (AML), acute lymphoblastic leukemia, T-cell lymphoma (TCL), and various solid tumors." (PMID 35865547, 2022). "Human CD47-blocking monoclonal antibodies have incredible efficacy in numerous patient-derived xenograft (PDX) preclinical models of breast, lymphoma, bladder, colon, glioblastoma, lung, acute lymphocytic leukemia, and acute myeloid leukemia." (PMID 31540045, 2019). "Currently, ten clinical trials are underway to test the efficacy of anti-CD47 agents (Hu5F9-G4, TTI-621, or CC-90002) as monotherapy or in combination with chemotherapy or target therapy to treat acute myeloid leukemia, colorectal cancer, solid tumor, and non-Hodgkin’s lymphoma." (PMID 30062558, 2018). "However, it has been shown that the disruption of CD47-SIRPα interaction by a blocking antibody against human CD47 (B6H12.2) enables phagocytosis of Acute Myeloid Leukemia Stem Cells (AML LSC) and Acute Lymphoid Leukemia (ALL) cells in vitro and inhibits tumor engraftment in vivo." (PMID 28061465, 2017). "Notably, magrolimab (an anti-CD47 antibody) has shown encouraging activity, particularly in combination with azacitidine in patients with myelodysplastic syndromes (MDS) and acute myeloid leukemia (AML), and is now being evaluated in a range of cancers, both hematologic and solid." (PMID 41601654, 2026).
acute myeloid leukemia (continued). "Acute myeloid leukemia (AML) is a cancer of hematopoietic stem/progenitor cells (HSPC), and similar to other types of cancers, leukemic blasts show enhanced levels of CD47." (PMID 34944878, 2021). "Similarly, CD47 has been found playing important roles in hematological malignancies, including in non-Hodgkin lymphomas (NHL), lymphoblastic lymphoma/acute lymphoblastic leukemia (LBL/ALL), acute myeloid leukemia (AML) and multiple myeloma (MM)." (PMID 34717705, 2021). "Magrolimab, a humanized anti-CD47 monoclonal antibody, was evaluated in combination with venetoclax plus either azacitidine or mitoxantrone/etoposide/cytarabine (MEC) in a Phase 2 trial involving patients with difficult-to-treat acute myeloid leukemia (AML)." (PMID 41303525, 2025). "For acute myeloid leukemia (AML) cells expressing CD47 and TIM‐3 antigens, anti‐CD47 antibody (aCD47)‐functionalized protein nanogel particles (CR‐TNG) anchor to leukemia cells by binding CD47 and TIM‐3, blocking CD47‐SIRPα interactions to promote macrophage phagocytosis of AML cells." (PMID 40345158, 2025). "However, there is no final conclusion whether the expression of CD47 promotes the transformation of acute myeloid leukemia by affecting cell cycle related pathways." (PMID 35433462, 2022). "In this study, we first characterized CD47 expression in Acute Myeloid Leukemia (AML) patients (n = 213) and found that CD47 is highly expressed on both AML bulk and stem cells irrespective of the disease state." (PMID 28061465, 2017). "Furthermore, Anti-CD47 antibody therapy disrupts the signal on CD34+CD38- leukemic stem cells, enhancing macrophage-mediated phagocytosis and achieving durable remissions in preclinical Acute Myeloid Leukemia (AML) models." (PMID 40881675, 2025).
glioma (91 papers, 2015 to 2026). A benign or malignant brain and spinal cord tumor that arises from glial cells (astrocytes, oligodendrocytes, ependymal cells). "Our analysis revealed a positive correlation between HIF-1α and CD47 gene expression in gliomas, with an associated correlation coefficient of 0.22." (PMID 39781344, 2025). "These nanoparticles induced glioma-associated myeloid cell phagocytosis of tumor cells via CD47–PD-L1 ligation, and activation of T cell–supportive myeloid cell phenotypes due to STING agonist–mediated effects." (PMID 38226619, 2024). "Immunohistochemical (IHC) analyses of 75 human glioma specimens with different grades (II–IV) showed that CD47 expression levels were positively associated with grade levels of glioma." (PMID 37541303, 2023). "Supporting this idea, it has been shown that a constant activation of β-catenin is needed for glioma progression, and increased levels of its target genes, such as CD47, have been associated with high-grade GBM." (PMID 31921125, 2019). "CD47 was associated with glioma stem-like cells and predicts a worse prognosis for patients." (PMID 40895574, 2025). "Additionally, a recent report shows that TMZ-induced ER stress is dependent on MGMT deficiency which potentiates CD47 blockade and increases glioma cell phagocytosis." (PMID 33391535, 2021). "Transcriptional analysis of glioma patients revealed that high CD47 mRNA expression levels were associated with decreased progression-free and overall survival, suggesting that CD47 expression levels may serve as a clinically relevant prognostic factor." (PMID 33117364, 2020). "Although both M1 and M2 subtypes demonstrate a robust response to CD47-SIRPα disruption, the stronger M1 antitumor response and associated cytokine profile suggest a clinical value from enhancing the M1 macrophage response toward gliomas and other solid tumors." (PMID 27092773, 2016). "Blockade of the CD47–SIRPα axis, a critical “don’t eat me” signal exploited by glioma cells, has demonstrated preclinical efficacy." (PMID 40867316, 2025). "Subsequently, we examined CD47 gene expression in both low-grade and high-grade gliomas using the GEPIA database." (PMID 39781344, 2025). "In another study, a triple-membrane hybrid composed of erythrocytes, U251 glioma cells, and macrophages integrated key membrane markers from each source—CD47 for immune evasion, CD44 for glioma targeting and BBB transport, and CD86 for immune modulation." (PMID 40624508, 2025). "It promotes tumor cell migration and invasion by interacting with CD47, and its silencing inhibits glioma growth and enhances sensitivity to anti-angiogenic therapy." (PMID 40885689, 2025). "CD47 expression correlates with poor prognosis in solid tumors, including glioma, and antibody-mediated targeting of this receptor increases tumor attack by myeloid cells." (PMID 40844085, 2025). "This virus selectively replicates in glioma cells, prompting them to secrete anti-CD47 IgG into the tumor microenvironment while avoiding release into the systemic circulation." (PMID 40867316, 2025). "An in vivo study found increased GBM phagocytosis following anti-CD47 treatment, whereas another model demonstrated minimal effects on glioma growth with anti-CD47 monotherapy." (PMID 40361384, 2025). "Specifically, CD47/SIRPα has been explored for its role in helping glioma cells to evade the phagocytic capabilities of microglia." (PMID 38893093, 2024). "Assessing CD47 expression of 75 human glioma specimens of different grade with immunohistochemical staining revealed that less than 30% tumor cells are CD47-positive in grade 4 gliomas, and the percentage is even lower in low-grade gliomas." (PMID 38786045, 2024). "Blocking this myeloid checkpoint CD47-SIRP⍺ axis using anti-CD47 antibody therapy was shown to limit tumor growth in both adult and pediatric gliomas and also promoted M1 activation of TAMs." (PMID 38254796, 2024).
glioma (continued). "Retrospective clinical studies have highlighted the significance of CD47 in glioma patients, observing that patients with lower overall survival rates expressed higher levels of CD47 and the expression levels inversely correlated with histopathologic grading." (PMID 38893093, 2024). "Demonstrating the efficacy of our approach, recombinant anti‐CD47 monoclonal antibodies, when incorporated into subsurface‐injected hydrogel solutions, exhibited cytotoxic activity against infiltrative high‐grade glioma xenografts in the rodent brain." (PMID 39553428, 2024). "Work with glioma stem cells (GSCs) has elucidated other mechanisms of CD47 regulation in this population of cells." (PMID 39194679, 2024). "In this review, we examined the role of phagocytic cell death in gliomas and strategies to modulate the balance between “don’t-eat-me” CD47/SIRPα and “eat-me” CALR/STC1 axes for therapeutic benefits." (PMID 38786045, 2024). "CD47, also known as "integrin-related protein," is thought to enhance the invasion and progression of high-grade glioma." (PMID 38396140, 2024). "Low-grade glioma showed a similar decreased survival trend with higher CD47 mRNA that approached significance at a mean cutoff and became significant with cutoff optimization or when median expression was used as a cutoff." (PMID 39201643, 2024). "A second study demonstrated that nanoparticles encapsulating a STING agonist and coated with dual anti-CD47/anti–PD-L1 antibodies mediated robust antitumor efficacy in murine gliomas." (PMID 38226619, 2024). "Our study demonstrates this platform can deliver recombinant anti‐CD47 monoclonal antibodies into sub‐surface xenograft high‐grade glioma tumors and observe bioactivity comparable to a commercially available alternative." (PMID 39553428, 2024). "CRISPR-Cas9 gene editing technology was then used to knock out the CD47 gene in several glioma cell lines." (PMID 37408232, 2023). "Targeting immune checkpoint CD47 via blocking the CD47-SIRPα pathway has been studied a lot in glioma." (PMID 37063864, 2023). "Glioma cells express high levels of CD47, which binds signal regulatory protein alpha of microglia, to release a “do not eat me” signal and suppress phagocytosis of microglia." (PMID 37462801, 2023). "We demonstrated here that CD47 expression levels correlated with the grades of human gliomas and with a poor prognosis in GBM patients." (PMID 37541303, 2023). "Of note, CD47, which is known to be upregulated in glioma stem cells, binds to SIRPα on the surface of macrophages to exert a “don't eat me” signal, thus contributing to immune evasion of the tumor cells by preventing phagocytosis by macrophages." (PMID 37791581, 2023). "The highly expressed anti-phagocytic factor CD47 in tumors is well-studied and recapitulated in our orthotopic syngeneic glioma cell line CT-2A28." (PMID 36959214, 2023). "Lastly, M2 TAMs promote immune evasion of glioma cells by binding to the “don’t eat me” signal molecule CD47, which is overexpressed on the cell surface of gliomas." (PMID 37234776, 2023). "In contrast, preclinical studies with humanized anti-CD47 antibodies have shown promising antitumor effects in pediatric glioma patient-derived xenograft models." (PMID 36594466, 2023). "In this way, gliomas‐targeting peptides are anchored to the N‐terminus of exosomal membrane protein CD47, which remarkably enhances the cellular uptake of exosomes by glioma cells." (PMID 37206219, 2023). "Analyses of glioma patient survival showed that the patients with high CD47 expression had a shorter survival time than those with low expression of CD47." (PMID 37541303, 2023). "Consistently, human GBM, including GSC7‐11 and GSC6‐27 primary GBM cells, or mouse glioma cells, exhibited higher expression levels of CD47 than either normal human astrocytes (NHA) or mouse normal brain tissues, respectively." (PMID 37541303, 2023).
glioma (continued). "Anti-CD47 antibody therapy increased the phagocytic activity of macrophages to glioma stem cells, decreased cancer stemness, and resulted in a significant inhibition of tumor growth." (PMID 35740975, 2022). "IHC analysis revealed that the three essential FAO enzymes CPT1A, CPT2, and ACAD9 were increased 86.96, 84.78, and 76.09% respectively in the recurrent gliomas, companied with 82.6% CD47 enhancement." (PMID 35314680, 2022). "Combining TMZ with CD47 blockade enhances the glioma cells phagocytosis and increases antigen cross-presentation, leading to more efficient T cells priming and anti-tumor immune responses in vivo." (PMID 35967394, 2022). "CD47 was reported as highly expressed in glioma cells and glioma stem cells, directly related to cell growth and differential potential." (PMID 35054787, 2022). "TSP-1/CD47 interactions have an important role in the modulation of glioma cell invasion and angiogenesis in GBM." (PMID 35054787, 2022). "Anti-CD47 was also proved to increase tumor-infiltrating CD8 + T cells that suppressed glioma cells and cancer stem cells." (PMID 35135556, 2022). "The CD47 blockade inhibited tumor growth and prolonged survival in immunocompetent mouse glioma models." (PMID 35054787, 2022). "SIRPα-Fc blocks CD47-SIRPα impressively, also triggering autophagy of glioma cells thus promoting survival in GBM models, and the prognosis is better with chloroquine." (PMID 35135556, 2022). "Studies have shown that CD47 is overexpressed in almost all types of tumors and tumor stem cells, including gliomas, acute myeloid leukemia, non‐Hodgkin's lymphoma, and breast cancer." (PMID 34363319, 2021). "Further, dropping the expression level of CD47 and SIRPα on glioma cells and macrophages resulted from the combination treatment suggests the deteriorating anti-phagocytic ability of glioma." (PMID 34671362, 2021). "Glioma cells induce the expression of the surface protein CD47 (“don’t eat me” signal), which inhibits TAM phagocytic activity." (PMID 33766119, 2021). "In a similar mechanism, CD47 antibody can promote the phagocytosis of glioma cells in the central nervous system by activating TA‐MG." (PMID 34363319, 2021). "It is worth pointing out that this effect has been attributed to overexpression of CD47 on glioma cells, which binds to SIRPα on the phagocytic cells to inhibit their phagocytic activity." (PMID 33802571, 2021). "Transcriptomic analysis of human gliomas has shown that high expression of CD47 correlates with overall survival, which makes CD47 a novel prognostic marker." (PMID 34168976, 2021). "In this study, glioma-targeting peptides were added to the N terminus of exosomal CD47, which enhanced the CD47-exosome (Exo-T) uptake in glioma cells." (PMID 33691652, 2021). "A recent report revealed that administration of RRx‐001, an anti‐CD47‐SIRPα small molecule with vascular normalizing properties, prior to temozolomide or irinotecan results in increased drug uptake in orthotropic glioma tumors." (PMID 34363319, 2021). "The main reasons for the delayed testing of CD47 antibodies in clinical gliomas are related to the concerns about the antibody itself and the possible resistance of gliomas to such therapy." (PMID 34363319, 2021). "CD47 is a transmembrane protein overexpressed in glioma cells that binds to the receptor SIRPA on the surface of monocytes/macrophages and MG cells inhibiting phagocytic functions and allowing tumors to escape the innate immune surveillance." (PMID 34168976, 2021). "Over the course of glioma-macrophage co-culture experiments, we found interesting results with CD47 and SIRPα expression." (PMID 32020472, 2020). "A recent report, exploring the efficacy and targets of the phagocytosis checkpoint inhibitor anti-CD47, demonstrated that MG-TAMs are important effectors of glioma cell phagocytosis contributing to overall survival of glioma-bearing mice." (PMID 33154756, 2020).